MAL (mal, T cell differentiation protein (MAL blood group))
Description:
May be involved in vesicular trafficking from the Golgi apparatus to the cell membrane. Plays a role in the maintenance of the myelin sheath, and in axon-glia and glia-glia interactions.
Synonyms: MVP17; VIP17; HLD28
Tractability: Antibody: UniProt places it where antibodies can reach, with high confidence; UniProt predicts a signal peptide or a membrane-spanning region; its Gene Ontology location is reachable by antibodies, with medium confidence.
Gene: Protein-coding gene on chromosome 2 (95,025,677 to 95,054,932, forward strand). Ensembl gene ENSG00000172005.
Subcellular location: Membrane; Cell membrane
Subcellular location (Human Protein Atlas): Golgi apparatus; Basal body; Centrosome
Gene Ontology:
Molecular function: protein binding; structural constituent of myelin sheath; lipid binding; peptidase activator activity involved in apoptotic process
Biological process: protein insertion into plasma membrane; apical protein localization; apoptotic process; cell differentiation; central nervous system development; membrane raft polarization; myelination; protein localization to paranode region of axon
Cellular component: apical plasma membrane; endoplasmic reticulum; membrane raft; plasma membrane; membrane; hinge region between urothelial plaques of apical plasma membrane; plasma membrane raft
Genetic constraint (gnomAD): Loss-of-function variants: 5 observed, 14.96 expected, observed/expected ratio (o/e) 0.33, 90% interval 0.17 to 0.7. The upper end of that interval is the gene's LOEUF score, 0.7, which puts it in group 2 of 6, group 1 being the genes least tolerant of losing a copy. Missense variants: 200 observed, 189.2 expected, observed/expected ratio (o/e) 1.06, 90% interval 0.94 to 1.19. Synonymous variants: 96 observed, 84.13 expected, observed/expected ratio (o/e) 1.14, 90% interval 0.97 to 1.35.
Homologues: Orthologues: chimpanzee MAL (99% identical), rat Mal (89% identical), macaque MAL (87% identical), mouse Mal (87% identical), guinea pig MAL (84% identical), dog MAL (75% identical), rabbit MAL (56% identical), zebrafish malb (52% identical), tropical clawed frog mal (50% identical), zebrafish mala.1 (44% identical), zebrafish mala.2 (44% identical), Caenorhabditis elegans F28H1.4 (27% identical), and 1 more. Paralogues in human: MALL (41% identical), MAL2 (39% identical), CMTM8 (29% identical), PLLP (27% identical), CMTM4 (21% identical), PLP2 (21% identical), MARVELD1 (20% identical), CMTM3 (16% identical), CMTM6 (16% identical), CMTM7 (16% identical), CMTM5 (16% identical), CMTM2 (15% identical), and 2 more.
Diseases named in the same sentence as MAL in open-access papers:
MAL is named in the same sentence as 111 diseases in open-access papers, as found by Europe PMC text mining. Sharing a sentence is not in itself a finding about the gene and the disease. The quoted sentences say what the papers report.
cervical cancer (18 papers, 2011 to 2025). A primary or metastatic malignant neoplasm involving the cervix. "MAL (T-lymphocyte maturation-associated protein) is highly downregulated in most cancers, including cervical cancer (CaCx), attributable to promoter hypermethylation." (PMID 38461243, 2024). "In a study with 79 cases, DNA methylation of CADM1, MAL, and miR124-2 in cervical scrapes had been shown to be present in all cervical cancer cases." (PMID 41008854, 2025). "The integration of highly sensitive platforms like ddPCR and validated gene panels such as CADM1/MAL represents a promising direction in the development of molecular strategies for cervical cancer triage, particularly among HPV-positive women." (PMID 40564169, 2025). "Downregulated expression of MAL has been demonstrated in several cancers of epithelial origin, including cervical cancers, justifying its role as a tumour suppressor." (PMID 38461243, 2024). "The methylation pattern of CIN2 lesions was similar to CIN3 and cervical cancer for miR124 and MAL, but it resembled the methylation pattern of low-grade lesions for CADM1." (PMID 37047452, 2023). "Methylation analyses of cervical cancer tissue have shown that CADM1/MAL methylations are present in up to 99% of all squamous cell carcinomas and 92% of all adenocarcinomas." (PMID 36010947, 2022). "ROC analysis for CADM1/MAL as a combined marker resulted in a significant area under the curve (AUC) of 0.872 (95% confidence interval: 0.743–1.000) for differentiation of cervical cancer patients and healthy donors." (PMID 36010947, 2022). "CADM1 methylation was detected in 18/24 (75%) of the cervical cancer plasma samples, MAL methylation in 10/24 (41.7%), and CADM1/MAL methylation in 20/24 (83.3%) of the samples." (PMID 36010947, 2022). "Promoter methylation and transcriptional silencing of MAL protein has been reported for numerous cancers, such as colon cancer, cervical cancer, gastric cancer, head and neck cancer, and oral squamous cell carcinoma." (PMID 32841292, 2020). "More importantly, MAL gene is frequently methylated in cervical cancer indicating its role in virus-related epithelial malignancy." (PMID 21535891, 2011). "In parallel to CADM1 we analysed MAL promoter methylation which was shown to be relevant in the viral oncogenesis of cervical cancer." (PMID 21535891, 2011). "Especially, the promoter methylation of the genes cell adhesion molecule 1 (CADM1) and myelin and lymphocyte protein (MAL) has been extensively studied in cervical tissue and smears and could frequently be observed in the development of cervical cancer." (PMID 36010947, 2022). "Like EBVaGC, HPV infection correlates with the silencing of MAL in cervical cancer." (PMID 32841292, 2020). "This is consistent with previous reports in which MAL promoter hypermethylation was detected in cervical disease as well as several cancers, including non-small cell lung cancer, head and neck squamous cell carcinoma, cervical cancer, ovarian cancer, gastric cancers, and colorectal cancer." (PMID 26992238, 2016). "PAX1, MAL, and CADM1 have been proposed as tumour suppressor genes involved in the development and progression of cervical cancer." (PMID 40564169, 2025). "Here, we established a liquid biopsy-based assay to detect MAL and CADM1 methylation in cell free DNA of cervical cancer." (PMID 36010947, 2022). "Methylation analyses of cervical cancer tissue have shown that cell adhesion molecule 1 (CADM1) and myelin and lymphocyte protein (MAL) methylation are present in over 90% of all cervical high-grade neoplasias and invasive cervical cancers." (PMID 36010947, 2022). "Exemplarily, follow-up samples were collected from three cervical cancer patients and tested for CADM1 and MAL methylation." (PMID 36010947, 2022). "In cfDNA samples of 24 cervical cancer patients, CADM1/MAL methylation was detected in 83.3% of the cases." (PMID 36010947, 2022).
cervical cancer (continued). "This study aimed to evaluate the performance of methylation status of three tumor suppressor genes (CADM1, FAM19A4, and MAL) and HPV genotyping in detection of cytologic and histologic abnormalities in cervical cancer screening." (PMID 30608989, 2019). "They found that in tissue the CADM1/MAL combination was superior to discriminate each, CIN3 and cervical cancer from normal tissue/CIN1 with methylation-positivity rates of 97% (CIN3) and 99% (cervical cancer)." (PMID 35725812, 2022). "Various host cell methylated genes such as SOX1, PAX1, JAM3, EPB41L3, CADM1, and MAL have been investigated for predicting cervical lesions, with PAX1 gene methylation showing the most significant correlation with the progression of cervical intraepithelial neoplasia and cervical cancer occurrence." (PMID 39155349, 2024). "CADM1 and MAL methylation was detected in seven (63.6%) and three (27.3%) of the 11 non-metastatic cervical cancer patients (FIGO IA-IIB), respectively; nine (81.8%) patients were positive for either MAL and/or CADM1." (PMID 36010947, 2022).
ovarian carcinoma (15 papers, 2009 to 2024). A malignant neoplasm originating from the surface ovarian epithelium. "Another study suggests that MAL methylation could also be used as a biomarker in nasopharyngeal carcinomas, which is a tumor associated with Epstein–Barr virus, and in epithelial ovarian cancers positive for high-risk human papillomavirus." (PMID 37345137, 2023). "Furthermore, elevated levels of MAL transcripts in ovarian cancer cell lines have been associated with resistance to cisplatin, indicating a possible implication of MAL in determination of in vitro platinum resistance." (PMID 28545541, 2017). "Since AURKA and MAL have been implicated in ovarian cancer pathology and are, therefore, functionally important rather than the outcome of a deregulation side effect, they are promising nominees to include in a panel of novel biomarkers for the detection of ovarian cancer." (PMID 31336942, 2019). "Furthermore, MAL methylation was associated with platinum sensitivity in epithelial ovarian cancer." (PMID 26992238, 2016). "First, MAL is overexpressed in ovarian cancer and certain types of lymphomas and appears to promote tumor progression." (PMID 35093120, 2022). "Among all the investigated genes, AURKA and MAL expression levels showed the best correlation with progression free survival (PFS) and the overall survival (OS) of ovarian cancer patients, and high expression levels were associated with a poor prognosis." (PMID 31336942, 2019). "In ovarian cancer, MAL expression was reported mostly in clear-cell and serous histotypes and its increased expression was observed in short-term compared to long-term survivors." (PMID 28545541, 2017). "MAL2 (Mal, T Cell Differentiation Protein 2), a transmembrane protein of the MAL proteolipid family, is upregulated in a number of malignancies, such as breast, colorectal, pancreatic, or ovarian cancer, has been shown to correlate with invasion and worse prognosis." (PMID 35445910, 2022). "The analysis revealed that many of the embryonic and cell development genes are fairly high expressed in ovarian cancer including FOXL2, GATA4, NR5A1, AMHR2, MAL and WIPF3." (PMID 31744494, 2019). "Eight immune factors (IFT57, MAL, ANXA4, SCRN1, LTBR, KIFAP3, HSPA5, and LTN1) were positively correlated with poor prognosis of ovarian cancer, whereas six immune factors (PSMB9, FOXJ1, CTSH, MIF, CTSD, and PSMB8) were negatively correlated with poor prognosis of ovarian cancer." (PMID 34109184, 2021). "In ovarian cancer, unlike most carcinomas in which the MAL gene is hypermethylated and there is no MAL expression, MAL is expressed and the MAL gene is hypomethylated at the transcription start site region, although it is methylated at an upstream region." (PMID 33946345, 2021). "However, unlike a previous proposal, it does not predict any effect of MAL expression in the response to platinum-based chemotherapy of ovarian cancer patients." (PMID 37345137, 2023). "However, there is no direct evidence of such an oncogenic role, since the link between high levels of MAL correlate and the poor prognosis of B-cell lymphomas and ovarian cancer does not necessarily mean that MAL induces the transformation of normal cells in neoplastic cells." (PMID 33946345, 2021).
gastric cancer (11 papers, 2008 to 2024). A primary or metastatic malignant neoplasm involving the stomach. "Epstein–Barr virus-associated gastric cancer is associated with genome-wide DNA hypermethylation of the host CpG islands, including the MAL gene." (PMID 33946345, 2021). "The aim of this study was to analyse the prevalence of MAL promoter hypermethylation and the association with mRNA expression in gastric cancers and to correlate methylation status to clinicopathological data." (PMID 19002170, 2008). "Conversely, in gastric cancer, MAL promoter hypermethylation was associated with better DFS." (PMID 26992238, 2016). "This indicates that other regulatory mechanisms of MAL silencing also exist in gastric cancer, which may include DNA copy number loss, other epigenetic mechanisms, altered expression of transcription factors regulating MAL or microRNAs targeting the MAL gene." (PMID 19002170, 2008). "It is interesting that the expression of exogenous MAL in gastric cancer cell lines reduces the viral titer, probably interfering with late steps of the viral replicative cycle such as the formation of viral particles or their budding from the cell." (PMID 33946345, 2021). "MAL has previously been reported to be a metastasis suppressor in esophageal cancer, gastric cancer, and head and neck squamous cell carcinoma and seems to confer survival advantages for relevant patients." (PMID 33672337, 2021). "Of the 17 gastric cancer tissue samples tested for MAL mRNA expression, 11 (64.7%) were methylated for M1, 11 (64.7%) for M2 and 9 (52.9%) samples showed methylation of both regions." (PMID 19002170, 2008). "Aim of this study was therefore to analyse promoter hypermethylation of MAL in gastric cancers, its relation to gene silencing and to determine its clinical value as a prognostic marker." (PMID 19002170, 2008). "Gastric carcinomas with M2 promoter methylation showed significantly lower expression of the MAL gene compared with M2 unmethylated gastric cancers (P=0.01)." (PMID 19002170, 2008). "Two out of 17 gastric cancers showed reduced MAL mRNA expression whereas the gene was unmethylated for both promoter regions." (PMID 19002170, 2008). "In particular, a tumor suppressor activity was demonstrated in esophageal tumors, as well as in colorectal and gastric cancer, while an intense MAL protein expression was detected in specific types of renal carcinoma and in thyroid follicular cell-derived carcinoma." (PMID 28545541, 2017). "The finding that inactivation of MAL by methylation gives a better prognosis for the patients may seem contradicting with a putative tumour suppressor function of this gene in gastric cancer." (PMID 19002170, 2008). "Altogether, these results pinpoint MAL as a putative tumour-suppressor gene with a role in gastric cancer, which may serve as an independent prognostic marker for clinical outcome of gastric cancer patients." (PMID 19002170, 2008). "In this study we show that MAL might have a similar role in gastric cancers, as methylation of MAL is detected at high frequency in gastric cancers and not in normal gastric mucosa samples." (PMID 19002170, 2008). "Results showed lower expression of MAL in gastric cancers methylated for the M1 or M2 region." (PMID 19002170, 2008). "Results of this study show that MAL may serve as a prognostic marker in gastric cancer, as patients with tumours methylated for the M2 region show significantly better survival compared with patients with tumours unmethylated for MAL or methylated only for the M1 region." (PMID 19002170, 2008). "Expression of MAL, which occurs at intermediate- to late-stage T cell differentiation, is downregulated or absent in a variety of tumor tissues, such as gastric cancer and LUAD and corresponds with advanced tumor progression." (PMID 35273597, 2022).
gastric cancer (continued). "RASSF1A, p14ARF, and MGMT; CHRNA3, DOK1, and GNMT; p16, hMLH1, MINT1, MINT2, MINT12, MINT25, and MINT31; APC, CDH1, MHL1, CDKN2A, CDKN2B, and RUNX3; CDH1; DKK3; PTEN; MGMT; TFPI2; CACNA2D3; PCDH10; SOX2; MAL; and COX2 were previously reported to be hypermethylated in gastric cancer." (PMID 26121593, 2015). "In summary, this study shows frequent promoter hypermethylation of MAL in gastric cancers, and not in normal gastric mucosa samples." (PMID 19002170, 2008).
lymphoma (9 papers, 2020 to 2024). A malignant (clonal) proliferation of B- lymphocytes or T- lymphocytes which involves the lymph nodes, bone marrow and/or extranodal sites. "The evidence that MAL is a putative receptor of the epsilon toxin of Clostridium perfringens, the expression of MAL in lymphomas, the hypermethylation of the MAL gene and subsequent loss of MAL expression in carcinomas are also presented." (PMID 33946345, 2021). "MAL expression in this type of lymphoma is an independent risk factor for adverse outcome." (PMID 33946345, 2021). "With regard to the expression of MAL in lymphomas, IHC and flow cytometry analyses showed MAL to be overexpressed in primary mediastinal large B-cell lymphomas, although this was not the case in diffuse large B-cell lymphomas and other B-cell derived tumors." (PMID 37345137, 2023). "Specifically, MAL overexpression allowed the differentiation of acute from chronic adult T-cell leukaemia/lymphoma, and primary mediastinal large B-cell lymphoma from DLBCL, in which it is sporadically expressed." (PMID 35409379, 2022). "MAL is expressed in human T cells, myelin forming cells, polarized epithelial cells as well as in cancer cells and lymphomas." (PMID 33345332, 2021). "In addition, MAL acts as a tumour progression factor in some kinds of lymphoma." (PMID 35409379, 2022). "Interestingly, MAL overexpression was reported in ~20% of investigated lymphoma, and a whole exome sequencing in human recently revealed that MAL SNP R81C activated its downstream signaling to enhance NF-κB gene expression, whose constitutive activity is characteristic of B cell lymphoma." (PMID 33072109, 2020).
colorectal cancer (8 papers, 2008 to 2021). A primary or metastatic malignant neoplasm that affects the colon or rectum. "Among primary colorectal carcinomas, those harbouring promoter hypermethylation of MAL (n = 13) expressed somewhat lower levels of MAL mRNA compared with the unmethylated tumours (n = 3), although not statistically significant." (PMID 18346269, 2008). "The level of MAL mRNA expression in cell lines (n = 46), primary colorectal carcinomas (n = 16), and normal mucosa (n = 3) was assessed by quantitative real time PCR." (PMID 18346269, 2008). "High expression of MAL promoted metastasis in colorectal cancer." (PMID 34109184, 2021). "A study has confirmed that MAL serves as a bridge between TLR2/TLR4- and MyD88-mediated signaling to orchestrate downstream inflammatory responses and regulate intestinal homeostasis and colitis-associated colorectal cancer in mice." (PMID 32099532, 2020). "However, among colorectal carcinomas and cell lines, MAL protein and gene expression seemed to be lost or reduced in all samples, including the minority with unmethylated MAL promoters." (PMID 18346269, 2008). "Bibliographic search evidenced that MAL, BANK1, CXCR2, and KCNJ15 genes play a tumor suppressive role in different types of cancer, including colorectal cancer, B-cell lymphoma, and renal cell carcinoma." (PMID 32825087, 2020). "Promoter hypermethylation of the genes CNRIP1, FBN1, INA, MAL, SNCA, and SPG20 was frequent in both colorectal cancers (65-94%) and adenomas (35-91%), whereas normal mucosa samples were rarely (0-5%) methylated." (PMID 21777459, 2011). "These genes in combination with the previously reported MAL and SPG20 resulted in a biomarker panel with a sensitivity of 94% for colorectal cancers and 93% for adenomas, and a specificity of 98%." (PMID 21777459, 2011). "Co-methylation, here defined as simultaneous hypermethylation of two or more of the six gene promoters (CNRIP1, FBN1, INA, MAL, SNCA, and SPG20), was found in 99% of the colorectal cancer test set samples and 2% of the normal mucosa samples." (PMID 21777459, 2011). "CNRIP1, FBN1, INA, MAL, and SNCA promoter methylation was analyzed quantitatively (qMSP) in the colorectal cancer (n = 74; median age 71 years) and normal mucosa (n = 51; median age 55 years) test sets." (PMID 21777459, 2011). "Hypermethylation of the selected markers (MAL, PRIMA1, PTGDR and SFRP1) can result in reduced gene expression and may contribute to the formation of colorectal cancer." (PMID 26482433, 2015).